BRCA1 (BRCA1 DNA repair associated)
Diseases named in the same sentence as BRCA1 in open-access papers (continued):
Sharing a sentence is not in itself a finding about the gene and the disease.
cancer (continued). "Thus, firstly, we identified all rare variants both exome-wide and cancer-associated gene panel-wide (492 genes) in 54 BC patients from BRCA1 and BRCA2-negative families with elevated BC risk and compared their relative incidence in 120 geographically matched controls." (PMID 30947698, 2019). "However, given the ubiquitous nature of DNA replication stress and DSB DNA repair, it is not clear whether genomic instability alone is sufficient to account for luminal-to-basal transition and subsequent cancer development in BRCA1 mutation carriers." (PMID 30995943, 2019). "Furthermore, some studies indicate that the cancer risk of BRCA1 and BRCA2 mutation carriers might be reduced by a healthy lifestyle (e.g. no smoking, physical activity)." (PMID 31370837, 2019). "However, HR deficiency is not limited to cancers carrying a BRCA1 mutation." (PMID 30683142, 2019). "The c.181T > G (p.Cys61Gly) alteration is one of the most common pathogenic BRCA1 founder mutations in Europe and a well‐established high‐risk variant, whereas the deleterious p.Arg1699Gln mutation is hypomorphic and was suggested to confer intermediate cancer risk." (PMID 31347298, 2019). "However, it has also been shown that the cancer risk varies by type and location of BRCA1 mutation." (PMID 30136106, 2019). "Moreover, many studies have reported that BRCA1 SNP is associated with cancer risk." (PMID 29492227, 2018). "Finally, elucidation of the mechanisms underlying the synthetic lethality between RAD52 and BRCA1/224–26 could identify potentially attractive therapeutic approaches for cancers in which BRCA1/2 is mutated." (PMID 30250272, 2018). "Recent success in treating BRCA1/2 deficient cancers, and our data showing that resistant cells with MMR mutations are sensitive to TMZ and ABT-888, leads us to speculate that treatment of sensitive tumours with a PARP inhibitor might thwart the emergence of MMR-mediated TMZ resistance." (PMID 30153289, 2018). "In this study, we established the prevalence and spectrum of the constitutional pathogenic variants in the BRCA1/2 and 23 other cancer-related genes that may play a role in the predisposition to OC, in a large Polish population of 333 unselected OC individuals." (PMID 30441849, 2018). "Thus, a therapeutic regimen that includes inhibitors for the DNA repair pathway, a tumor-specific platinum drug, together with radiotherapy may prove to be an effective way of treating and managing the cancer burden due to BRCA1 and BRCA2 mutations." (PMID 29459887, 2018). "In addition, multigene panel testing could identify up to 50% more individuals with cancer susceptibility gene mutations in comparison with testing only for BRCA1 and BRCA2 (BRCA)." (PMID 29566657, 2018). "In addition, estimating the tumor mutational burden, which is supposed to be higher in BRCA1/2 deficient cancers, might be another method to identify BRCAness." (PMID 30544963, 2018). "Interestingly, cancer-predisposing BRCA1 mutations abolished BRCA1-mediated transcriptional activation, suggesting a possible role of transcriptional regulation in mediating tumor suppressing function of BRCA1." (PMID 30558184, 2018). "Despite the rapid growth of next‐generation sequencing allowing for simultaneous testing of multiple genes linked to cancer risk, the clinical impact of pathogenic variants in genes beyond BRCA1 and BRCA2, especially in terms of CBC risk, is still largely unknown." (PMID 29733510, 2018). "Thus, BRCA1 mutation in cancer cells can impart increased mesenchymal phenotype in CAFs." (PMID 30224826, 2018). "Likewise, several observations in breast cancer patients led to the hypothesis that low‐penetrance cancer susceptibility polymorphisms act as modifier genes in BRCA1/BRCA2 mutation carriers and non‐carriers to increase cancer risk." (PMID 29507082, 2018). "However, the extent of developing other cancers in BRCA1 mutation carriers is less clear." (PMID 30652068, 2018).
cancer (continued). "Certain SNPs in DNA glycosylase genes could affect negatively to the general performance of the BER pathway and contribute by increasing the levels of genome instability and hence to a higher cancer risk, especially in presence of a defective BRCA1 or BRCA2 background." (PMID 29383107, 2017). "Furthermore, patients with BRCA1 mutation cancers had worse TTP and OS compared to those with BRCA2 mutation cancers, and our data suggest that this could potentially be related to an increased incidence of RDR." (PMID 29262651, 2017). "Nested within the questionnaire developed for the European InCRisC (International Cancer Risk Communication Study) project were 14 items assessing expected benefits (8 items) and drawbacks (6 items) of the process of breast/ovarian genetic cancer testing (BRCA1/2)." (PMID 28570656, 2017). "In this study, our objective was to characterize women at-risk for hereditary BC regarding their status of BRCA1 mutation and methylation and to correlate these results with the levels of gene expression, histopathological and clinical data, as well as with prognosis and family history of cancer." (PMID 27926510, 2017). "In addition, a cancer genome is a snapshot of the genome of a cancer cell that started clonal expansion to give rise to the sampled part of the tumour, and the number of cell divisions and length of time between the BRCA1/2 loss and the beginning of this expansion is impossible to tell." (PMID 27452521, 2017). "Thus, patients with BRCAness features may benefit from therapies known to be effective in patients bearing cancers with BRCA1 and BRCA2 mutations." (PMID 28099152, 2017). "These risks vary significantly according to (a) age at disease diagnosis in carriers of identical mutations, (b) the cancer site in the individual who led to the family’s ascertainment, (c) the degree of family history of the disease, and (d) the type and location of BRCA1 and BRCA2 mutations." (PMID 27796716, 2017). "However, it is not known whether other important pathways of DNA damage repair operating in cancer cells contribute to and influence the pathologic response in a cisplatin neoadjuvant chemotherapy setting in BRCA1-associated TNBCs." (PMID 27626685, 2016). "The response of BRCA1 mutation-associated cancers to both PARP inhibitors and cisplatin-based chemotherapeutic agents has driven the interest in identifying tumours with a similar DNA-repair deficient phenotype, so that these difficult to treat patients might also benefit from targeted therapies." (PMID 27463681, 2016). "Deficiency in DNA damage repair is commonly found in many cancers, however, it remains unclear whether and how this defect may influence the pathological response after cisplatin neoadjuvant chemotherapy in BRCA1-associated TNBCs." (PMID 27626685, 2016). "Therefore, mutations affecting the BARD1/BRCA1 heterodimer structure may confer an increase in cancer risk." (PMID 27197561, 2016). "Although further experiments are needed to clarify the molecular effects exerted by the c.5406+2T>C splice variant on the BRCA1 protein, the results reported herein could explain the pathogenicity of this novel mutation, particularly in view of the various cases of cancer in the analyzed family." (PMID 28009814, 2016). "Considering these facts, the associated immune responses to few aberrant cells in breast tissue, that may give rise to malignancies due to impaired DNA-repair mechanisms by BRCA1/2 mutations, may potentially be driving the earliest stages of cancer development." (PMID 27659691, 2016). "Consequently, identifying BRCA1 mutations that result in low basal expression levels might help stratify cancer risk." (PMID 27534398, 2016). "Thus, our data suggest that 6-TG may be indeed a promising therapeutic agent against BRCA1-deficient cancers provided that cancer cells are HR-deficient and have a functional mismatch repair machinery." (PMID 27313062, 2016).
cancer (continued). "Moreover, although a tumour suppressive role of BRCA1 in DNA damage repair and cell cycle checkpoint has been demonstrated, the exact reason whereby BRCA1 deficiency causes predominantly cancers of the breast and ovary also remains largely unknown." (PMID 25531315, 2015). "Lastly, there is evidence to suggest BRCA1 deficient cancers may be sensitive to PARP inhibitors." (PMID 26152113, 2015). "This raises the question of whether or not interference with specific olfactory agents could be an effective means of reducing cancer risk in young individuals with germline BRCA1 mutations who wish to postpone risk-reducing surgery in order to preserve their fertility." (PMID 26488398, 2015). "Loss of PTEN expression might be a starting event in a variety of BRCA1-associated cancers." (PMID 25426449, 2014). "Human studies suggest that elevated PRA expression is generally associated with a poor prognosis, and there is evidence that genetic predisposition to cancer development due to mutations in BRCA1 or BRCA2 genes leads to PRA overexpression, which may play a role in disease progression." (PMID 25515784, 2014). "Interestingly, cancer-associated point mutations of BRCA1 disrupt the BRCA1-RNA Pol II interaction." (PMID 24704793, 2014). "Recently, genetic modifiers have been shown to play a role in determining cancer risk in other mendelian tumor syndromes, such as BRCA1/2-related breast and ovarian cancer, and SNP genotyping could be of help in identifying a ‘modifier locus’ to predict the risk of cancer in HPS patients." (PMID 25208626, 2014). "A recent large scale study of available cancer sequencing data reported identification of multiple mutation signatures in 30 types of cancer, and certain mutation signatures have been linked to probable causes such as age, smoking, BRCA1/2 mutations, or MMR deficiency." (PMID 24901304, 2014). "Thus, determining whether BRCA1 heterozygosity confers haploinsufficiency on HMECs for any of the multiple, known, BRCA1 functions is a potentially valuable step in achieving a better understanding of BRCA1 mutation-driven cancer predisposition." (PMID 25400221, 2014). "BRCA1 methylation was significantly associated with the downregulation of BRCA1 expression (P<0.001) and the frequency of BRCA1 methylation was greater in the carcinomas of patients whose tumor was bilateral than that of patients with a unilateral carcinoma (P=0.015)." (PMID 24944674, 2014). "Furthermore, as a PARP1 inhibitor, bufalin might be effective in those cancer cells with BRCA1/2 deficiencies, a concept which warrants further investigation." (PMID 23762475, 2013). "Cancers with mutations in BRCA1/2 may be particularly promising to study." (PMID 23369278, 2013). "However, the exact mechanism by which RT reduces incidence of BRCA1-associated cancer remains unclear." (PMID 23210696, 2012). "Given the emerging evidence that BRCA1 tumors originate from luminal progenitor cells, our observations suggest that preferential and long-lasting elimination of luminal ductal epithelium may partly underlie the mechanism of RT-associated reduction in recurrence of BRCA1-associated cancer." (PMID 23210696, 2012). "The novel screening principle proposed and demonstrated in this work could hold immediate implications for patients with known cancer risks such as genetic predispositions (BRCA-1, Nf1 mutations) or patients with a history of cancer who are at high risk for recurrence." (PMID 21589655, 2011). "We also compared the frequency of pathologic features and biomarker expression of the 12 ER- and 9 ER+ BRCA1-associated cancers for which wt BRCA1 allele status could not be determined to ensure that this group was similar to those cancers which were successfully subjected to LOH analysis." (PMID 21080930, 2010).
cancer (continued). "Although some experiments raise the possibility that BRCA1-deficient cells may be resistant to anti-cancer agents targeting the microtubules (such as vinca alkaloids and taxanes), no preclinical in vivo studies have ever demonstrated taxane resistance in BRCA2-deficient cells." (PMID 20877358, 2010). "The present study provides the first evidence to demonstrate that BRCA1-mutation related cancer risk and malignant transition may be associated with accumulation of potent pro-inflammatory lipid PAF and over expression PAFR in non-malignant ovarian epithelial cells." (PMID 20576130, 2010). "Prediction of BRCA1/2 carrier status, and hence selection of women for mutation screening, may be substantially improved by combining tumour pathology with family history of cancer." (PMID 20482762, 2010). "However, before speculating on specific mechanisms by which BRCA1/2 mutations might contribute to non-cancer conditions, confirmatory studies are essential." (PMID 19277124, 2009). "Indeed, 9 of 10 BRCA1-associated BC demonstrated complete pathological response to the cisplatin treatment, i.e. these women have good chances to be ultimately cured from the cancer disease." (PMID 19379506, 2009). "Consequently, we cannot identify specific conditions that might explain the observed association between the three BRCA1/2 Ashkenazi founder mutations and non-cancer mortality." (PMID 19277124, 2009). "Indeed, BRCA1 dysfunction in sporadic basal-like cancers has been reported, and conditional deletion of exons encoding the C-terminus of BRCA1 in the mammary gland of mice results in basal-like cancer." (PMID 19007432, 2008). "While reduction in cancer-specific mortality is the gold standard for surveillance tools, there is a pressing need to supplement mammography in high-risk women, particularly for BRCA1 and BRCA2 mutation carriers who are diagnosed with a high rate of interval tumors, roughly 50%." (PMID 16800895, 2006). "Inter-individual variation in the speed at which BRCA1 mutation carriers develop cancer is likely to be influenced by environmental factors, but may also be affected by co-inheritance of other disease modifying genes which interact with the BRCA1 cellular pathway." (PMID 16563154, 2006). "It is likely that defective HR in BRCA1/2-mutant tumour cells also underlies their hypersensitivity to IR and DNA crosslinking agents, which may ultimately impact on the chances of combination cancer therapy to achieve tumour eradication." (PMID 15054444, 2004). "Germline pathogenic variants in BRCA1 and BRCA2 confer disproportionately elevated cancer risks in breast and ovarian tissues, yet the basis for this tissue specificity remains incompletely understood." (PMID 42079105, 2026). "This is further supported by the finding of the group of Sharon Cantor and our data presented here, confirming the PARPi resistance when MDC1 was depleted in human MDA-MB-436 (BRCA1-mutated) and PEO1 (BRCA2-mutated) cancer cells." (PMID 41408464, 2026). "Classic examples include PARPis in BRCA1/2‐deficient tumours and EZH2 inhibition in ARID1A‐deficient cancers." (PMID 41537447, 2026). "Using a CRISPR/Cas9‐based combined screening approach that integrates RNAi with CRISPRn and CRISPRi, researchers identified DNA ligase I (LIG1) as a novel synthetic lethal target in BRCA1‐mutant cancers." (PMID 41537447, 2026). "A recent meta-analysis of 21 studies that addressed prophylactic interventions (chemoprevention and RRS) for healthy women with BRCA1 or BRCA2 variants, focused on both cancer risk reduction and mortality outcomes." (PMID 41488281, 2026). "And our results also show that the dietary compound I3C can prevent estrogen-induced DNA damage, and suggest that I3C can be a potential cancer-preventive therapeutic agent for BRCA1 carriers." (PMID 41896346, 2026). "Germline loss-of-function mutations in BRCA1 and BRCA2 markedly increase susceptibility to breast, ovarian, and other cancers." (PMID 42274517, 2026).
cancer (continued). "In a prospective, multicenter cohort study involving 2,482 women with BRCA1 or BRCA2 mutations, researchers assessed the impact of risk-reducing mastectomy or BSO on cancer outcomes." (PMID 41488281, 2026). "Hence, our work reveals a previously unknown function of MDC1 in RF biology, a role that contributes to DNA damage induced by genotoxic agents and the response of BRCA1- or BRCA2-deficient tumors to clinically relevant anti-cancer drugs, such as PARPi and cisplatin." (PMID 41408464, 2026). "This study demonstrates the value of population-scale EHR linkages, and that survivors of BC carrying BRCA1/BRCA2 PVs are at elevated cancer risks." (PMID 39475295, 2025). "This extended version allows for a more comprehensive assessment of cancer worry, particularly tailored to BRCA1/2 carriers — a group with distinct genetic risks and psychological needs." (PMID 40390061, 2025). "Our analysis indicated that the BRCA1 regulon in malignant tumor cells comprises a greater number of TGs and exhibits a more intricate regulatory network than those found in various immune cell types, which display simpler networks." (PMID 41354912, 2025). "At the same time, somatic missense, indels, and deep intronic variants in genes such as BRCA1, BRCA2, and others involved in HR repair have been associated with cancer and treatment resistance." (PMID 40146757, 2025). "Cancer development in BRCA1 carriers is a multi-step process, which is triggered by several factors and mechanisms that are not clearly understood." (PMID 41283387, 2025). "No participants had a personal history of GC, 47% had a personal history of a cancer other than GC, and one (6.7%) participant (BRCA1 carrier) had a family history of GC." (PMID 41256354, 2025). "This in turn helps the BRCA1-mutant cancer cells to activate the DNA damage checkpoint, enter G2/M arrest, and ultimately undergo apoptosis." (PMID 40136510, 2025). "Colorectal (SIR, 4.80 [95% CI, 2.62 to 8.05]) and endometrial (SIR, 2.92 [95% CI, 1.07 to 6.35]) cancer SIRs were increased in BRCA1 PV carriers." (PMID 39475295, 2025). "Due to the early onset of cancer, the patient conducted germline testing that revealed BRCA1, BRCA2 and RB1 losses, and amplification of the MYC gene." (PMID 40104509, 2025). "Cytoplasmic localization of BRCA1/2, which typically reflects impaired functionality, has been documented in various cancers, including breast, prostate, gastric, colorectal, and pancreatic cancers." (PMID 40224184, 2025). "Pathogenic germline mutations in BRCA1 and BRCA2 are known to cause hereditary breast and ovarian cancer syndrome (HBOC), leading to cancer development at a relatively young age." (PMID 40249378, 2025). "The wider effects of BRCA1 in other cancers and its potential as a therapeutic target are still being investigated." (PMID 40141415, 2025). "There are recommended measures for prevention and earlier diagnosis of cancers in patients identified as BRCA1 and BRCA2 PGV carriers, which are the most common cancer-predisposing PGVs." (PMID 40123843, 2025). "Since the majority of BRCA1/2-related cancers are triple negative or luminal B, it follows the fact that such patients had a higher likelihood of having been talked about genetic testing by their physicians." (PMID 40338860, 2025). "When NE invaginations are artificially induced, they increase the sensitivity of BRCA1-deficient cancer cells to olaparib, providing a proof of principle for combining the targeting of PARP and NE deformability in cancer therapy." (PMID 40527886, 2025). "We examined γH2AX, which is the phosphorylation of Ser139 of histone H2AX and well-recognized as the biomarker of DSB, in BRCA1-proficient cancer cells." (PMID 40299557, 2025).